ELK1 (ETS transcription factor ELK1)
Diseases named in the same sentence as ELK1 in open-access papers (continued):
Sharing a sentence is not in itself a finding about the gene and the disease.
neurodevelopmental disorder (1 paper, 2022). A behavioral and cognitive disorder with onset during the developmental period that involves impaired or aberrant development of intellectual, motor, or social functions. "Our results suggest that the MAPK/ERK/ELK1 axis potentially contributes to the pathogenesis caused by CHD8 mutations in human neurodevelopmental disorders." (PMID 36575212, 2022).
ELK1 also shares sentences with these, for which no sentence is quoted: non-small cell lung carcinoma (6 papers); breast tumor (4); endothelial dysfunction (4); sarcoma (3); acute promyelocytic leukemia (2); colonic adenocarcinoma (2); Down syndrome (2); esophageal cancer (2); esophageal squamous cell carcinoma (2); myocardial infarction (2); Parkinson disease (2); Acute monoblastic leukemia (1); acute respiratory distress syndrome (1); amyloid (1); autism (1); Burkitt lymphoma (1); C. perfringen infection (1); carcinoma in situ (1); central nervous system diseases (1); chronic myelogenous leukemia (1); CNS tumors (1); cognitive decline (1); cognitive disorder (1); Costello syndrome (1); fibrosarcoma (1); gastrointestinal tumor (1); glomerulonephritis (1); hydronephrosis (1); idiopathic pulmonary fibrosis (1); intracerebral hemorrhage (1).
A further 20 diseases each share a sentence with ELK1 in 1 paper.